RN7SL480P (RNA, 7SL, cytoplasmic 480, pseudogene)
Gene: Miscellaneous RNA gene on chromosome 1 (150,211,632 to 150,211,925, forward strand). Ensembl gene ENSG00000266187.
Homologues: Orthologues: chimpanzee Metazoa_SRP (98% identical), macaque Metazoa_SRP (91% identical). Paralogues in human: RN7SL1 (89% identical), RN7SL2 (88% identical), RN7SL3 (87% identical), RN7SL444P (84% identical), RN7SL45P (84% identical), RN7SL126P (83% identical), RN7SL336P (83% identical), RN7SL296P (83% identical), RN7SL828P (82% identical), RN7SL113P (82% identical), RN7SL220P (82% identical), RN7SL357P (82% identical), and 704 more.